RPS26P3 (ribosomal protein S26 pseudogene 3)
Synonyms: bA338L20.1
Gene: Processed pseudogene on chromosome 9 (9,090,898 to 9,091,245, forward strand). Ensembl gene ENSG00000212829.
Diseases named in the same sentence as RPS26P3 in open-access papers:
RPS26P3 is named in the same sentence as 2 diseases in open-access papers, as found by Europe PMC text mining. Sharing a sentence is not in itself a finding about the gene and the disease. The quoted sentences say what the papers report.
ovarian carcinoma (1 paper, 2019). A malignant neoplasm originating from the surface ovarian epithelium. "All these findings indicated that RPS26P15, AC004057.1, RPS26P31, RPS26P6, RPS26P3 and RPS26P47 were the most potential pseudogenes in regulating hsa-miR-363-3p in ovarian cancer." (PMID 31794425, 2019). "Among 56 predicted pseudogenes, only 6 pseudogenes (RPS26P15, AC004057.1, RPS26P31, RPS26P6, RPS26P3 and RPS26P47) were significantly upregulated in cancer samples (compared to normal samples) and advanced stage of ovarian cancer (compared to early stage ovarian cancer)." (PMID 31794425, 2019).
cancer (1 paper, 2019). A tumor composed of atypical neoplastic, often pleomorphic cells that invade other tissues. "Finally, only 6 pseudogenes, RPS26P15, AC004057.1, RPS26P31, RPS26P6, RPS26P3 and RPS26P47 were significantly upregulated in cancer tissues when compared with normal controls." (PMID 31794425, 2019).